CD44 (CD44 molecule (IN blood group))
Diseases named in the same sentence as CD44 in open-access papers (continued):
Sharing a sentence is not in itself a finding about the gene and the disease.
uveitis (4 papers, 2020 to 2025). An inflammatory process affecting a part of or the entire uvea. "Among those genes, a few are already known to be implicated in uveitis, such as E and P selectins, CD44, IL-33 and Lcn2." (PMID 32183784, 2020). "This NETs‐CD44‐IL‐17A feedback loop is a potential therapeutic target for uveitis." (PMID 40013981, 2025). "Since CD44 is expressed in reactive microglia cells from Cngb1-knockout retinas and from retinas following endotoxin induced uveitis, we analyzed retinal sections and retinal flatmounts from 12-week-old ST/ST mice that were co-immunostained for IBA1 to visualize microglia/macrophages and CD44." (PMID 39095775, 2024).
acute pancreatitis (3 papers, 2022 to 2025). An acute inflammatory process that leads to necrosis of the pancreatic parenchyma. "Three targeted genes, Btg2, Zbp1, and Cd44, indirectly support the association between PAITA and tRF3-Thr-AGT in the mechanisms underlying acute pancreatitis initiation." (PMID 35045793, 2022).
Alexander disease (3 papers, 2019 to 2024). Alexander disease (AxD) is a rare neurodegenerative disorder of the astrocytes comprised of two clinical forms: AxD Type I and Type II manifesting with various degrees of macrocephaly, spasticity, ataxia and seizures and leading to psychomotor regression and death. "In a mouse model of Alexander disease, a CNS degenerative disorder caused by mutations in GFAP, we found that protoplasmic astrocytes of the hippocampus and isocortex became CD44+ as the disease progressed." (PMID 38247821, 2024). "Increased CD44 immunoreactivity in the astrocytic processes was also shown in human patients with tuberous sclerosis and the mouse model of Alexander disease, which are conditions accompanied by seizures." (PMID 37296604, 2023). "CD44 heterogeneity within activated astrocytes has been previously identified in mouse models of Alexander disease." (PMID 31551718, 2019).
allergic rhinitis (3 papers, 2020 to 2024). Inflammation of the nasal mucous membranes caused by an IgE-mediated response to external allergens. "Besides, KLF4 regulates immune response-related genes including IL1RL1, CD274, and CD44 in human nasal epithelial cells of allergic rhinitis." (PMID 38245772, 2024).
ameloblastoma (3 papers, 2014 to 2026). The most common odontogenic tumor, arising from the epithelial component of the embryonic tooth and usually affecting the molar-ramus region of the mandible or maxilla. "SMO gene mutation or CD44 dysregulation can reportedly contribute to a higher recurrence of ameloblastoma." (PMID 36242034, 2022). "SOX2 and CD44 immunoexpression were significantly higher in conventional ameloblastoma." (PMID 42196620, 2026). "Studies have reported that CD44 is highly expressed in ameloblastomas." (PMID 25161776, 2014).
amyotrophic lateral sclerosis (3 papers, 2015 to 2024). Amyotrophic lateral sclerosis (ALS) is a neurodegenerative disease characterized by progressive muscular paralysis reflecting degeneration of motor neurons in the primary motor cortex, corticospinal tracts, brainstem and spinal cord. "Finally, CD44 expression is increased in a mouse model of amyotrophic lateral sclerosis (ALS;)." (PMID 26448752, 2015).
Anaplastic Thyroid Carcinoma (3 papers, 2014 to 2026). "In the present study, we demonstrated that EpCAM, together with CD44 and claudin-7, is associated with the phenotype of anaplastic thyroid cancer both in the established cell lines and clinical specimens." (PMID 24727741, 2014). "Thus, the anaplastic thyroid cancer cell lines expressed variant isoforms of CD44 in contrast to the reduced CD44s expression." (PMID 24727741, 2014). "The upregulation of cell surface markers such as CD44, CD133, and ALDH1A1 has been linked to a poorer prognosis and increased resistance to chemotherapy and radiotherapy in both differentiated (DTC) and undifferentiated thyroid carcinomas (UTC)." (PMID 39595993, 2024). "Comparison of localization of EpCAM and CD44 expression in clinical anaplastic thyroid cancers (N = 37)." (PMID 24727741, 2014). "Although direct interaction of EpCAM, CD44 variants, and claudin-7 was not examined in our study, the results suggest that complexes of EpCAM with CD44 variants and claudin-7 may be associated with the aggressive phenotype of anaplastic thyroid cancer." (PMID 24727741, 2014).
anemia (3 papers, 2013 to 2025). A reduction in the number of red blood cells, the amount of hemoglobin, and/or the volume of packed red blood cells. "To specifically determine whether DON‐induced anemia results from defective erythroid development, we analyzed erythroblasts and reticulocytes using the surface markers Ter119 and CD44." (PMID 40899647, 2025). "While CD44+ CD51– TNCs also expanded 14 days after 5FU treatments in p32−/− bone marrow, while severe anemia was observed in the peripheral blood, suggesting p32-deficiency blocks erythroid differentiation of CD44+ CD51– TNCs." (PMID 33103089, 2020). "A study using cultured splenic ProE and bone marrow cells obtained from mice infected with the anemia-inducing strain of Friend leukemia virus (FVA) suggests that later erythropoietic developmental stages may resolve better when stained with antibodies against CD44." (PMID 24303107, 2013). "In particular, Ly6D– CD44+ CD51– TNCs are erythroid-committed cells able to expand and differentiate into mature erythrocytes under hemolytic stresses such as sickle cell crisis and PHZ-induced anemia in mice." (PMID 33103089, 2020).
B-Cell Lymphoma (3 papers, 2011 to 2023). "Further studies are needed to assess the prognostic value of CD5 expression and loss of CD44 in old dogs with B-cell lymphoma." (PMID 35448684, 2022). "Concerning B-cell lymphomas, CD34 expression, loss of CD44, and expression of CD5 were the most represented aberrancies in our caseload." (PMID 35448684, 2022). "The most represented aberrancies were: CD5-, CD4-CD8-, and CD3- in T-NOS lymphomas, CD21+, CD4-CD8-, and CD3- in TZLs, and CD34+, CD44-, and CD5+ in B-cell lymphomas." (PMID 35448684, 2022).
carcinoids (3 papers, 2019 to 2023). "The adhesion molecule CD44 has prognostic implications in typical carcinoids and is expressed in most lung carcinoids." (PMID 38001701, 2023). "Atypical carcinoids with proliferation index ≥5% and loss of OTP and/or CD44 were at high risk for distant metastases." (PMID 35805004, 2022). "In this series of 171 carcinoids, we could show that loss of OTP and CD44 expression was strongly associated with unfavorable disease outcome." (PMID 35805004, 2022). "In contrast, patients who presented with disseminated disease at baseline or developed metastases during follow-up could be identified by atypical carcinoid morphology in combination with a high proliferation index (Ki-67 ≥ 5%) and loss of OTP and/or CD44 expression." (PMID 35805004, 2022). "In more recent study by Papaxionis and colleagues, CD44 and OTP were incorporated with carcinoid gradation in a multivariate model with similar results." (PMID 35805004, 2022). "To the best of our knowledge, we firstly isolated CSCs of a typical carcinoid, which were positive for the prominent CSC markers CD44, CD133 and nestin, confirming their stem cell properties." (PMID 31804333, 2019). "After radical surgical resection, however, extensive follow-up may be futile in case of a carcinoid with a favorable biomarker profile (low mitotic count, low Ki-67 expression, and normal OTP/CD44 expression), which was 47% in our cohort." (PMID 35805004, 2022). "In addition to the widely used carcinoid classification, a comprehensive analysis of histopathological variables including Ki-67, OTP, and CD44 could assist in the determination of distant metastasis risks of bronchial carcinoids." (PMID 35805004, 2022). "Patients (n = 76) with carcinoids harboring a favorable marker profile (Ki-67 < 5%, mitotic count < 2 per 2 mm2, and OTP or CD44 positivity) exclusively did not develop distant metastases during follow-up." (PMID 35805004, 2022). "Patients who did not develop metastasis in follow-up had typical carcinoids with proliferation index <5% and positive OTP and CD44." (PMID 35805004, 2022).
cervical adenocarcinoma (3 papers, 2013 to 2021). An adenocarcinoma arising from the cervical epithelium. "IL4 and IL13 can upregulate CD44 expression in human cervical adenocarcinoma cell lines and colonic epithelial cell lines." (PMID 35187044, 2021). "CD44 is therefore not considered to be a biomarker for cervical adenocarcinoma stem cells." (PMID 24260061, 2013).
cervical tumor (3 papers, 2021 to 2025). "In addition, the literature supports an exponential relationship between CSC abundance and CD44 levels within cervical tumours as well as the ability of high‐risk HPV oncogenes E6 and E7 to further promote an increase in CSCs, and thus a subsequent increase in CD44 expression." (PMID 40888184, 2025). "Together, CD44 down-regulation and E-cadherin overexpression indicate Sal-Doc SE-NP could inhibit CSCs or induce CSCs transforming, which is one key target for suppression of cervical tumor progression." (PMID 33657950, 2021).
clear cell carcinoma (3 papers, 2013 to 2024). "CD44 expression was observed in a few cases of basal cell adenocarcinoma (BCAC) or clear cell carcinoma." (PMID 39858584, 2024). "The rates of positive expression of Lewis y antigen and CD44 in cases of clear cell carcinoma and endometrioid carcinoma were similar to those in the serous group, although the number of cases in these groups were small." (PMID 23468946, 2013). "As previously stated, the choice of CD44 isoform to be measured may be important, as was described in a study on a small series of clear cell carcinomas where CD44-10v expression predicted recurrence and death." (PMID 27590006, 2016).
coronary heart disease (3 papers, 2022 to 2025). "Significantly upregulated were gene regulators of VSMC differentiation, triggers of cell apoptosis, inflammation and coronary heart disease markers (Itih4, Tppp3, Slc25a39, CD44) in parallel to atheroprotective genes such as Morf4l2." (PMID 35163719, 2022). "As expected, levels of several EV antigens (CD8, CD8, CD1c, CD25, CD62P, CD42a, CD86, CD44) increased in subjects displaying both OD and established cardiac disease (coronary artery disease, or chronic heart failure), as compared with those with only OD or cardiac disease." (PMID 39702460, 2024). "Studies have shown that in patients with coronary heart disease, the mRNA expression of CD44 in the peripheral blood is significantly positively correlated with the Gensini score of the coronary arteries, which could reflect the degree of coronary artery stenosis." (PMID 40824771, 2025).
ductal carcinoma in situ (3 papers, 2014 to 2015). "The Notch signalling pathway has also been implicated in controlling the fate of putative stem cells in the normal human mammary gland and in the regulation of CD44+CD24- breast CSCs in both ductal carcinoma in situ (DCIS) and invasive carcinoma." (PMID 24919951, 2014).
E. coli infection (3 papers, 2011 to 2020). "It has been shown that endothelial surface expression of ICAM-1 and CD44 is significantly elevated upon E. coli infection but expression of ICAM-2, VCAM-1 or E-selectin in pulmonary endothelial cells is not affected." (PMID 27657497, 2016). "In addition, accumulation of soluble CD44 in the CSF was significantly reduced in KO mice compared with wildtype animals after E. coli infection, suggesting that α7 nAChR contributes to up-regulation of adhesion molecules induced by both nicotine and E. coli K1." (PMID 21966399, 2011).
endometrioid carcinoma (3 papers, 2013 to 2017). "More recently, it has been showed that CD133+ cells purified from endometrioid adenocarcinomas are resistant to cisplatin-induced and paclitaxel-induced cytotoxicity and express a peculiar gene signature consisting of high levels of matrix metalloproteases, interleukin-8, CD44, and CXCR4." (PMID 28531111, 2017).
glaucoma (3 papers, 2022 to 2024). Increased pressure in the eyeball due to obstruction of the outflow of aqueous humor. "In primary open-angle glaucoma, a progressive decrease in HA concentration within the ECM of the trabecular network results in a corresponding increase in CD44 accumulation, a degradant of CD44 that is cytotoxic to retinal ganglion cells." (PMID 35890371, 2022). "Examples of these include genetic models of glaucoma (MyocY437H mice), OHT induced by transduction of the TM with glaucoma-related genes (e.g., MYOC, TGFβ2, GREM1, CTGF, DKK1, SFRP1, CD44, Cre and inducible transgene models, genome editing), as well as glucocorticoid-induced OHT models." (PMID 35129590, 2022).
immune thrombocytopenia (3 papers, 2013 to 2015). "We previously determined that several CD44 antibodies could protect against passively-induced immune thrombocytopenia (ITP) while other CD44 antibodies themselves caused thrombocytopenia." (PMID 23785450, 2013). "While the standard treatment for immune thrombocytopenia is passive infusion of immunoglobulins, several anti-CD44 antibodies have been shown to ameliorate immune thrombocytopenia." (PMID 25954275, 2015). "As TLR4 is expressed on both macrophages and DC, we questioned whether IVIg or the CD44 antibody KM114 might utilize the TLR4 pathway in its amelioration of immune thrombocytopenia." (PMID 23940791, 2013). "Given that immune thrombocytopenia (induced by anti-platelet treatment) can ameliorate inflammatory arthritis, we hypothesized that the ameliorative effects of anti-CD44 treatment in inflammatory arthritis could potentially be mediated by their ability to cause thrombocytopenia." (PMID 23785450, 2013).
in situ carcinoma (3 papers, 2010 to 2024). A malignant epithelial neoplasm which is confined to the epithelial layer without evidence of further tissue invasion.
infertile (3 papers, 2012 to 2020). "Our findings highlighted an increased level of circulating OPN and CD44 in serum from infertile patients that inversely correlated with expression levels in endometrial tissue and positively correlated with levels secreted into biopsy media." (PMID 33047155, 2020). "PCOS patients were characterized by significantly higher follicular levels of CD44(v6) (age-adjusted r = 2072.7 pg/mL, P = 0.010) and MIP-1α (adjusted for age, cause of infertility, and follicular count in prestimulatory ovary r = 3111.7 pg/mL, P = 0.007)." (PMID 22007253, 2012). "The identification of treatments to modify the interaction between the ligand/receptor pair of CD44 and OPN may potentially contribute to the improved diagnostic status of infertile PCOS patients." (PMID 33047155, 2020). "Active smoking was associated with elevated follicular CD44(v6) levels (adjusted for age and cause of infertility r = 1227.8 pg/mL, P = 0.019 versus never smokers group) and sAPO-1/Fas levels (adjusted r = 464.9 pg/mL, P = 0.031 versus never-smokers group)." (PMID 22007253, 2012). "Our findings of lower levels of CD44(v6) in unexplained infertility and higher levels in PCOS and active smokers might reflect impaired apoptosis mechanisms in the ovaries of these patients." (PMID 22007253, 2012). "• Circulating levels of OPN, CD44 and inflammatory cytokines TNF-α and IFN-γ are altered in infertile PCOS patients." (PMID 33047155, 2020). "In infertile patients, inflammatory cytokines led to recruitment of NF-κB and STAT1 proteins to the OPN and CD44 promoters, resulting in their overexpression." (PMID 33047155, 2020). "• In infertile PCOS patients, high levels of oestrogens and inflammatory cytokines stimulate the recruitment of transcription factors to the OPN and CD44 promoters to enhance gene transcription." (PMID 33047155, 2020). "Therefore, this study aims to evaluate the endometrial expression and circulating levels of CD44 and OPN proteins in infertile patients diagnosed with PCOS." (PMID 33047155, 2020). "Therefore, this abnormal circulation of CD44 and OPN can be exploited as a possible biomarker for early diagnosis of infertility and further enhance current clinical practice in the diagnosis of endometrium receptivity status of patients." (PMID 33047155, 2020).
keloid (3 papers, 2016 to 2022). An irregularly shaped, elevated mark on the skin caused by deposits of excessive amounts of collagen during wound healing. "Later, several independent research groups successfully isolated keloid-derived mesenchymal-like stem cells (KMLSCs) in adult keloid tissue which expressed the MSC CD markers CD13, CD29, CD44, CD90, fibronectin, and vimentin." (PMID 32085797, 2020). "As miR-21-5p mimic induced the EMT and stem-like cells phenotype in keloid keratinocytes, to figure out whether keloid keratinocytes with the EMT phenotype also possess stem-like cell signature, double fluorescence staining for CD44 (green) and vimentin (red) was performed." (PMID 27596120, 2016).
metabolic syndrome (3 papers, 2013 to 2024). A cluster of metabolic risk factors for CARDIOVASCULAR DISEASES and TYPE 2 DIABETES MELLITUS. "To study this hypothesis, we examined the effect of the loss of CD44 expression on the development of various features of metabolic syndrome using CD44 null mice." (PMID 23505504, 2013). "Studies have suggested that CD44 may be involved in the development and progression of metabolic syndrome." (PMID 38809924, 2024). "Our analysis identified four essential genes—SPP1, IGF1, CD44, and FLT1—that serve as potential molecular links between Alzheimer’s and metabolic syndrome." (PMID 38809924, 2024). "Consequently, we have identified FLT1, SPP1, CD44, and IGF1 as the critical genes shared among the clusters in the PPI network of AD and metabolic syndrome." (PMID 38809924, 2024).
myelodysplastic syndrome (3 papers, 2023 to 2025). A clonal hematopoietic disorder characterized by dysplasia and ineffective hematopoiesis in one or more of the hematopoietic cell lines. "In patients with myelodysplastic syndromes (MDS), MSCs show a decreased expression of certain cell surface molecules, especially those involved in the interaction with HSPCs, including the adhesion molecules CD44 and CD49e (α5-integrin)." (PMID 37047305, 2023).
non-alcoholic fatty liver disease (3 papers, 2022 to 2024). "In patients with non-alcoholic fatty liver disease (NAFLD) higher levels of circulating and liver tissue CD44 were associated with more severe liver injury." (PMID 38603681, 2024).
ovarian clear cell cancer (3 papers, 2015 to 2022). An invasive malignant neoplasm that arises from the ovary and is characterized by a predominance of clear and hobnail malignant epithelial cells. "Expression of CD44, CD47 and c-met in ovarian clear cell carcinoma (OCCC)." (PMID 25658794, 2015).
parasitemia (3 papers, 2015 to 2022). "On the other hand, the frequency of both CD4+CD44+CD62L- and CD8+CD44+CD62L- T cells were increased at the peak of parasitemia." (PMID 32913355, 2020).
renal dysfunction (3 papers, 2013 to 2025). "The formation of a triple complex involving HA, CD44 and RHAMM on the cell surface shows promise as a targetable biomarker for early intervention to mitigate severe renal dysfunctions." (PMID 39050866, 2024). "Elevated plasma and urine HA, CD44 and RHAMM levels were notably observed in the severe renal dysfunction group." (PMID 39050866, 2024). "Our study demonstrates that upon LPS exposure, lack of CD44 impairs the early pro-inflammatory cytokine response, inflammatory cell migration/chemotaxis, endothelial activation, and therefore delays the onset of endotoxin shock-induced renal dysfunction." (PMID 24376813, 2013).